MTOR (mechanistic target of rapamycin kinase)
Diseases named in the same sentence as MTOR in open-access papers (continued):
Sharing a sentence is not in itself a finding about the gene and the disease.
tumor (continued). "It is also important to consider that long-term mTOR inhibitor treatment may be required, as discontinuation of mTOR inhibitors is typically associated with regrowth of tumours." (PMID 31333563, 2019). "It is also worth to underline that targeting mTOR cascade alone may have limited therapeutic efficacy because tumor cell proliferation could be fully sustained via the compensatory activation of the Ras/MAPK cascade." (PMID 31277283, 2019). "Aberrant mTOR activation can occur through oncogene stimulation or the loss of tumor suppressors." (PMID 29932116, 2018). "Finally, tumor metabolism (mTOR signaling) has been explored as a targetable mechanism in NF1-deficient tumor types using the small molecules everolimus and sirolimus." (PMID 29662612, 2018). "Abnormal activation of the mTOR signaling may provide explanation why UBTOR is downregulated or mutated in tumor tissues." (PMID 30080879, 2018). "Overall, these results suggest that the signal activation of both NF-κB and mTOR that was induced by tumor-secreted factors could be closely associated with glucose concentration in TCM." (PMID 30586442, 2018). "However, deregulated PTEN/mTOR activities have been implicated in various disorders including metabolic diseases, tumor formation and even senescence." (PMID 30158848, 2018). "Additionally, activation of PI3K/mTOR pathway from either mutation or gene amplification was positively correlated with tumor susceptibility to PI3K inhibitors in xenograft models." (PMID 31093356, 2018). "Calcineurin inhibitors have been associated with dose-dependent increased risk of malignancy and mTOR inhibitors have been proven to have a less cancerogenic profile and even anti-tumour properties, being used to delay progression of metastatic renal cell cancer." (PMID 30326848, 2018). "Intra-tumor heterogeneity shows on one hand the presence of different phenotypes within the tumor (mTOR mutation) or, on the other, heterogeneous mutation sites in the same genes (SETD2, KDM5 and PTEN), indicating a phenotype convergence in the evolution of the tumor." (PMID 29491834, 2018). "Indeed, RAPA, besides being an effective immunosuppressor, can cause a direct anti-tumor effect through the inhibition of mTOR, a serine/threonine kinase that controls cell size and proliferation and that is commonly deregulated in human cancers." (PMID 29915171, 2018). "Similarly, nuclear p-mTOR was significantly associated with a lower tumour grade (p = 0.0053, X2 test)." (PMID 29902261, 2018). "Since oxidative phosphorylation is impaired in RCC, co-activation of the Nrf2 pathway and the PI3K/Akt/mTOR pathway might cooperatively cause a shift of metabolism to aerobic glycolysis that enhances tumor cell growth." (PMID 29983865, 2018). "Furthermore, the tumor-suppressive effect was associated with inhibition of the phosphorylation of Akt and mTOR." (PMID 29371937, 2017). "Treating the mice with a drug that inhibits mTOR caused the tumours to shrink." (PMID 28695825, 2017). "Although STK11 is inactivated by a large spectrum of truncating mutation and behave as a tumor suppressor gene in different tumor models through mTOR inhibition, recent studies suggest that STK11 may also gain oncogenic properties." (PMID 26625312, 2017). "In these studies, mTOR inhibition was associated with significant anti-tumor activity." (PMID 28002802, 2017). "Our goal was to determine whether combined MDM2 and PI3K/AKT/mTOR targeting is associated with higher anti-tumor activity than single agent alone in preclinical models of WDLPS/DDLPS." (PMID 28903316, 2017). "The mutations in this tumor included 3 predicted high impact mutations in MTOR a regulator of stress response, OGT a glycosyltransferase that modifies a broad range of targets including H2B, AKT1, EZH2, PFKL, KMT2E/MLL5, MAPT/TAU and HCFC1, and FAM129B a negative regulator of apoptosis." (PMID 28415633, 2017).
tumor (continued). "Mammalian Target of Rapamycin (mTOR) is a well-known regulator of cell growth and proliferation, and dysregulation of mTOR by either oncogene activation or tumor suppressor loss can induce tumor growth in various malignant cell lines." (PMID 28187439, 2017). "Indeed, the mTOR pathway is constitutively activated in neurofibromin-deficient primary cells and tumours, and is regulated by phosphorylation and inactivation of the TSC2-encoded protein tuberin by AKT, ERK and RSK." (PMID 28637487, 2017). "Furthermore, another mechanism underlying tumour resistance to mTOR inhibition is the upregulation of autophagy." (PMID 28513565, 2017). "As activated AMPK directly and indirectly inhibits mTOR8, 9, 10, 11, 12, 13, 14, 15, the LKB1-AMPK pathway controls mTOR activity, e.g., upon aberrant activation of Akt, which occurs in various types of tumours with loss of function of PTEN or PI3-Kinase gain of function mutations." (PMID 28649994, 2017). "Meanwhile, p-mTOR was significantly associated with age (OR = 1.46, 95%CI 1.24–1.72, P < 0.001), tumor location (OR = 1.26, 95%CI 1.03–1.55, P = 0.03), depth of invasion (OR = 1.63, 95%CI 1.08–2.45, P = 0.02), and TNM stage (OR = 1.73, 95%CI 1.29–2.32, P < 0.001)." (PMID 29233126, 2017). "However, SHR8443 inhibited the phosphorylation of PI3K and mTOR downstream effectors in tumor cell lines harboring different mutations that modulated PI3K/AKT activity." (PMID 29296217, 2017). "However, responses of AML and other TSC-associated tumours to these mTOR inhibitors are partial and tumours that initially respond to treatment usually regrow after drug withdrawal." (PMID 28938574, 2017). "Tumour growth was associated with decreases in mTOR and p70S6K1 gene expression, as well as reduced expression of eIF4E, eIF5 and eIF2a, three factors involved in protein synthesis (the tumour effect was highly significant at P < 0.05)." (PMID 26847205, 2016). "Together, these data indicate that eIF4B functions downstream of STAT/Pim and PI3K/Akt/mTOR signaling in Abl transformants, and Ser422 phosphorylation is associated with synergic inhibitory effects on cell survival and tumor growth induced by combined blockage of Pim and PI3K/Akt/mTOR pathways." (PMID 26848623, 2016). "Our previous studies showed that temporal pharmacological inhibition of the mTOR pathway was sufficient to suppress the tumor development contributed by Fbxw7 loss, suggesting that the Fbxw7-mTOR pathway plays a major role in this radiation-induced carcinogenesis mouse model." (PMID 27376155, 2016). "Therefore, inhibition or deletion of mTOR in myeloid cells caused a defect CD11b+ Ly6ChighLy6G− M-MDSC differentiation in tumor-bearing recipients." (PMID 26833095, 2016). "Similarly, in breast CSCs, colony formation and tumor initiation abilities were mediated in PTEN deficient cells through activation of mTOR and downstream STAT3 signaling." (PMID 27826244, 2016). "Birt-Hogg-Dubé (BHD) syndrome is a rare inherited autosomal genodermatosis and caused by germline mutation of the folliculin (FLCN) gene, a tumor suppressor gene of which protein product is involved in mechanistic target of rapamycin (mTOR) signaling pathway regulating cell growth and metabolism." (PMID 27871249, 2016). "Liver kinase B1 (LKB1) is a tumor suppressor, and its loss might lead to activation of the mammalian target of rapamycin (mTOR) and tumorigenesis." (PMID 26877155, 2016). "Inhibition of mTOR sets up a unique molecular scenario whereby it is plausible that various aspects of tumour development could be inhibited while at the same time causing a general immunosuppression that protects allografts from rejection." (PMID 25699174, 2015).
tumor (continued). "In the late AB subpopulation we also identified mutations in PIK3C2B and RPTOR, which may sensitize the tumor to a number of drugs that target the PI3K/Akt/mTOR signaling pathways." (PMID 25729435, 2015). "We further demonstrated that the mTOR inhibitor, sirolimus, suppresses the tumor's growth, suggesting that mTOR inhibitors might be effective in control of FLCN-deficient RCC, especially in BHD renal tumorigenesis." (PMID 26418749, 2015). "mTOR activation mediates a differentiation into M2 macrophages while treatment with rapamycin induces differentiation into M1 macrophages associated with anti-tumor responses." (PMID 26180685, 2015). "Interestingly, we have also observed that the overexpression of PI3K/Akt/mTOR pathway biomarkers decisively associated with worst CSS in STn positive advanced stage tumours, which currently lack effective therapeutics." (PMID 26569621, 2015). "The finding that MTOR mutations are associated with worsened outcomes has prognostic relevance and suggests that this event may be a significant contributor to tumor progression." (PMID 26255626, 2015). "Our results demonstrated that sirolimus could effectively inhibit Flcn-deficient allograft tumor growth, suggesting that mTOR inhibitors may be effective in treating FLCN-deficient RCC." (PMID 26418749, 2015). "Our previous studies using mouse models showed that temporal pharmacological inhibition of the mTOR pathway was sufficient to suppress the tumor development contributed by Fbxw7 loss, suggesting that the Fbxw7-mTOR pathway plays a major role in this radiation-induced carcinogenesis mouse model." (PMID 26575021, 2015). "Overall, our data suggests that point mutations in the mTOR pathway may lead to downstream mTOR hyperactivation through multiple different mechanisms to confer a proliferative advantage to a tumor cell." (PMID 26255626, 2015). "Notably, the FASN inhibitor in combination with the mTOR inhibitor caused tumor regression and induced weight gain in mice bearing ER+/HER2+ tumors." (PMID 24866893, 2014). "In particular, S6K was phosphorylated in the tumor regions harboring the L2427P MTOR mutation." (PMID 25159823, 2014). "A decrease in PTEN might cause activation of the PI3K pathway, including Akt and mTOR, which leads to tumor development." (PMID 25366985, 2014). "In this case, despite parallel evolution of the four individual tumors, there is indeed evidence for convergence upon the PI3K-AKT-mTOR pathway with two independent MTOR mutations in tumors from the left kidney and proteomic evidence for pathway activation in all tumor regions." (PMID 25159823, 2014). "Studies have linked the role of ERK or mTOR to VEGF expression during tumour angiogenesis." (PMID 24779927, 2014). "Also, transcription of the Mirk gene itself is blocked in cycling cells through Akt/mTOR signaling causing Mirk to be highly expressed predominately in quiescent tumor cells." (PMID 25061503, 2014). "The identification of an ARID1A mutation in tumor one in the contralateral kidney to those tumors harboring MTOR mutations may further illustrate convergence upon the PI3K-AKT-mTOR pathway." (PMID 25159823, 2014). "Next, we investigated whether temporal mTOR inhibition by rapamycin can prevent mice from Fbxw7 loss-induced tumor development." (PMID 23454868, 2013). "Aberrant activation of PI3K/AKT/mTOR signaling cascade has been implicated in tumor development." (PMID 24069385, 2013). "In this study, we investigated whether inhibition of mTOR signaling pathway by rapamycin was able to prevent the tumor development resulted from loss of Fbxw7 in mice." (PMID 23454868, 2013). "In this study we evaluated the ability of both PIK3CA genotype and the PIK3CA-GS to quantify the level of PI3K/AKT/mTOR pathway activation in a given tumor and its associations with anti-proliferative responses in ER-positive breast cancer treated with everolimus." (PMID 23301057, 2013).
tumor (continued). "Interdependency on PI3K/AKT activation of ARID1A mutated tumor clones might be a process that is targetable by small-molecule inhibitors of the PI3K/AKT/mTOR pathway." (PMID 24036443, 2013). "BEZ235 also caused a decrease in phospho-mTOR and phospho-Akt in tumor tissue lysates." (PMID 24042258, 2013). "Deregulation of mTOR signaling is frequently associated with tumor growth and angiogenesis." (PMID 23840271, 2013). "Our results in this study showed that temporal pharmacological inhibition of mTOR pathway after radiation was sufficient to suppress the tumor development contributed by Fbxw7 loss, suggesting that Fbxw7-mTOR pathway plays a major role in this radiation-induced carcinogenesis mouse model." (PMID 23454868, 2013). "NVP-BEZ235, which targets PI3K/Akt/mTOR pathway, induced growth arrest in 786-O that was associated with inhibition of Akt and S6 phosphorylation as well as the induction of apoptosis and reduction in markers of tumor cell proliferation." (PMID 24133625, 2013). "Tumour cells have shown high susceptibility to mTOR inhibitors." (PMID 23434669, 2013). "The tumor was resistant to PI3K/mTOR pathway inhibitors despite harboring a PIK3CA mutation." (PMID 23502469, 2013). "Inhibition of the mTOR pathway in skin was also closely associated with inhibition in tumor." (PMID 24403259, 2013). "The HBx-associated IKKβ/TSC1/mTOR signaling pathway may play a molecular switch that allows HBV-related HCC tumor progression." (PMID 22848663, 2012). "However, activation of the PI3K/AKT/mTOR pathway is implicated in all major mechanisms of radioresistance, including intrinsic radioresistance, tumor cell proliferation, and hypoxia." (PMID 22666248, 2012). "We hypothesized that loss of Pten expression could contribute to activation of this pathway and that patients with Pten-deficient tumours might particularly profit from treatment with mTOR inhibitors." (PMID 23139750, 2012). "The mTOR pathway is implicated in tumor development, and analogues of rapamycin – a natural antibiotic that specifically interferes with mTOR action (via an additional receptor protein) – are showing great promise as potential therapeutic agents for treating certain types of solid tumors." (PMID 21373201, 2011). "It is possible that activation of the Ras/Raf/MEK/ERK and Ras/PI3K/PTEN/Akt/mTOR survival pathways by additional mutations in upstream oncogenes may replace the tumor's initial oncogene addition." (PMID 21422497, 2011). "Loss of feedback inhibition in tumours treated with mTOR inhibitors (via increased expression of IRS-1) results in induction of AKT signalling, and may be responsible for the disappointing efficacy of mTOR antagonists in the clinic." (PMID 21909357, 2011). "In conclusion, our results taken together suggest that FLT3 mutations may lead to activation of mTOR signaling pathway and thus contribute to tumor cell survival and growth in AML." (PMID 21067588, 2010). "Inappropriate mTOR activation has been implicated in the pathogenesis of numerous tumor types." (PMID 19860903, 2009). "The results of preclinical and phase I studies, as well as data from biomarker studies showing oncogenic transformation in mTOR-linked pathways suggest that mTOR inhibitors may have anticancer activity in many tumor types." (PMID 19860903, 2009). "In a subset of tumours, reactivation of Akt was associated with an inferior clinical response, leading the researchers to conclude that combination mTOR plus PI3K inhibition may overcome this type of drug resistance." (PMID 22275966, 2008). "Importantly, this down-regulation is concurrently associated with increased sensitivity of RCC tumor cells to mTOR inhibitors, suggesting that lactotransferrin may serve as a predictive biomarker for therapeutic response." (PMID 41566198, 2026).
tumor (continued). "Excessive calcineurin‐inhibitor exposure and prolonged corticosteroid use have been associated with tumor progression through proangiogenic and mTOR pathway activation, whereas mTOR inhibitors, such as sirolimus and everolimus, exert antiproliferative effects, and may reduce recurrence risk." (PMID 41522472, 2026). "The impact of CMTM6 on macrophage polarization and its association with tumor progression were systematically evaluated through a series of in vitro and in vivo experiments, focusing on the induction of M2a macrophage polarization and activation of the mTOR signaling pathway." (PMID 40761779, 2025). "Additionally, tumor vascular density, which is correlated with tumor thickness, may provide a quantitative approach to follow up and evaluate the effects of mTOR inhibitors on TSC-associated RAHs." (PMID 40486194, 2025). "In addition, in vitro experiments also showed that ALT-1 (0, 80, 150, 200 μM) reduced the viability and proliferation of COLO205 and HCT116 cell lines, and downregulated the phosphorylation of proteins associated with the AKT/mTOR pathway to inhibit the growth of tumor cells." (PMID 40342991, 2025). "Interestingly, this down-regulation has also been associated with increased sensitivity of RCC tumor cells to mTOR inhibitors, suggesting that lactotransferrin expression may serve as a predictive biomarker for therapeutic efficacy." (PMID 40677703, 2025). "Collectively, these results suggest that the elevation of the RiBi pathway in cells at the EMT transitioning phase is associated with aberrant activation of ERK and mTOR signalings, which may, in turn, confer nascent protein synthesis capability to tumor cells for completing phenotypic changes." (PMID 39259576, 2024). "Notably, mutations in the mTOR gene could lead to collective activation of the downstream proteins p70S6K and eIF4, which are believed to be associated with tumor survival and treatment sensitivity." (PMID 38356720, 2024). "Thus, a pressing question remains unanswered in the clinic: should agents targeting signalling molecules of the AKT/mTOR axis, like alpelisib and capivasertib, be solely administered to patients whose tumours harbour genomic alterations of genes encoding for members of this pathway?" (PMID 39322687, 2024). "Importantly, mTOR activation may contribute to the elevated tumour risk observed in KTRs who receive TAC as part of their immunosuppressive therapy." (PMID 38341510, 2024). "Thus, further studies on the molecular mechanisms associated with drug targeting of mTOR and ferroptosis could provide new therapeutic insights in the anti-tumor field." (PMID 38583115, 2024). "However, while amino acid metabolism may play a role in tumor associated MDSCs, how amino acids affect MDSCs through the classical mTOR or GCN2 pathway requires further investigation." (PMID 37277776, 2023). "Furthermore, WNT/β-catenin pathway-mediated PIK3CA mutations may reduce the sensitivity of tumor cells to the dual PI3K/mTOR inhibitor." (PMID 37046703, 2023). "Another case study reported GBM organoids established from a patient recurrent GBM with PTEN mutation and mTOR hyperactivation displayed sensitivity for the mTOR inhibitor everolimus, which was then given to the patient and led to a significant reduction of the tumor size." (PMID 38596241, 2023). "Of note, mTOR signaling acted as a prevailing regulator in glycolysis and underlay the potential candidate for new combination immunotherapies, which may be beneficial for immunotherapy-refractory tumor patients." (PMID 37828561, 2023). "However, in terms of Retcome pathways, overexpressed GOT2 was positively associated with tumor-related pathways, such as “MTOR Signaling” (NES = 1.44, adj. p < 0.001), “Cellular Response To Hypoxia” (NES = 1.647, adj. p = 0.004), “Signaling By NOTCH4” (NES = 1.661, adj. p = 0.007)." (PMID 37693904, 2023).